MAEA (macrophage erythroblast attacher, E3 ubiquitin ligase)
Description:
Core component of the CTLH E3 ubiquitin-protein ligase complex that selectively accepts ubiquitin from UBE2H and mediates ubiquitination and subsequent proteasomal degradation of the transcription factor HBP1. MAEA and RMND5A are both required for catalytic activity of the CTLH E3 ubiquitin-protein ligase complex. MAEA is required for normal cell proliferation. The CTLH E3 ubiquitin-protein ligase complex is not required for the degradation of enzymes involved in gluconeogenesis, such as FBP1. Plays a role in erythroblast enucleation during erythrocyte maturation and in the development of mature macrophages (By similarity). Mediates the attachment of erythroid cell to mature macrophages; this MAEA-mediated contact inhibits erythroid cell apoptosis. Participates in erythroblastic island formation, which is the functional unit of definitive erythropoiesis. Associates with F-actin to regulate actin distribution in erythroblasts and macrophages (By similarity). May contribute to nuclear architecture and cells division events (Probable).
Synonyms: HLC-10; EMP; PIG5; GID9; p44EMLP; EMLP
Tractability: Antibody: UniProt places it where antibodies can reach, with high confidence; its Gene Ontology location is reachable by antibodies, with high confidence. PROTAC: UniProt records ubiquitination sites on it; ubiquitination databases record sites on it; its protein half-life has been measured.
Gene: Protein-coding gene on chromosome 4 (1,289,876 to 1,340,147, forward strand). Ensembl gene ENSG00000090316.
Subcellular location: Cytoplasm; Nucleus, nucleoplasm; Nucleus matrix; Cell membrane; Cytoplasm, cytoskeleton
Subcellular location (Human Protein Atlas): Nucleoplasm
Pathways (Reactome):
Metabolism: Regulation of pyruvate metabolism
Gene Ontology:
Molecular function: actin binding; ubiquitin protein ligase activity; ubiquitin-protein transferase activity
Biological process: cell adhesion; negative regulation of myeloid cell apoptotic process; proteasome-mediated ubiquitin-dependent protein catabolic process; regulation of mitotic cell cycle
Cellular component: actomyosin contractile ring; cytoskeleton; nuclear matrix; nucleoplasm; nucleus; plasma membrane; spindle; ubiquitin ligase complex; cytoplasm; cytosol; GID complex; actin cytoskeleton
Genetic constraint (gnomAD): Loss-of-function variants: 22 observed, 44.67 expected, observed/expected ratio (o/e) 0.49, 90% interval 0.35 to 0.7. The upper end of that interval is the gene's LOEUF score, 0.7, which puts it in group 2 of 6, group 1 being the genes least tolerant of losing a copy. Missense variants: 391 observed, 571.94 expected, observed/expected ratio (o/e) 0.68, 90% interval 0.63 to 0.74. Synonymous variants: 246 observed, 228.21 expected, observed/expected ratio (o/e) 1.08, 90% interval 0.97 to 1.2.
Homologues: Orthologues: macaque MAEA (100% identical), dog MAEA (99% identical), pig MAEA (99% identical), guinea pig MAEA (99% identical), mouse Maea (99% identical), rat Maea (99% identical), tropical clawed frog maea (95% identical), zebrafish maea (94% identical), chimpanzee MAEA (87% identical), Drosophila melanogaster Kaz (47% identical), Caenorhabditis elegans maea-1 (30% identical). Paralogues in human: RMND5A (23% identical), RMND5B (23% identical).
Diseases named in the same sentence as MAEA in open-access papers:
MAEA is named in the same sentence as 23 diseases in open-access papers, as found by Europe PMC text mining. Sharing a sentence is not in itself a finding about the gene and the disease. The quoted sentences say what the papers report.
type 2 diabetes (7 papers, 2013 to 2025). "MAEA is involved in erythroblast attachment to macrophages, and rs6815464 G > C was associated with type 2 diabetes in an East Asian GWAS meta-analysis." (PMID 40399988, 2025). "The MAEA locus was previously shown to be associated with type 2 diabetes in the present Japanese sample, but the remaining 9 loci have not been examined in an independent East Asian cohort." (PMID 24086726, 2013). "MAEA overexpression in primary mouse liver cells attenuates hepatic gluconeogenesis and reduces the risk of insulin resistance, which may improve type 2 diabetes mellitus." (PMID 35204186, 2022). "Intronic SNP rs6815464 on MAEA gene has been associated (P-value = 2E-20) with type 2 diabetes." (PMID 23844243, 2013). "Several type 2 diabetes mellitus (T2DM) susceptibility loci have been identified in or near GLIS3, PEPD, FITM2-R3HDML-HNF4A, KCNK16, MAEA, GCC1-PAX4, PSMD6, and ZFAND." (PMID 34822452, 2021). "It is reported that MAEA is a differentially methylated gene in Type-2 diabetes and idiopathic pulmonary fibrosis." (PMID 29933410, 2018). "Among them, MAEA and GLIS3 loci were significantly associated with type 2 diabetes after correction for multiple testing." (PMID 27053236, 2016). "Moreover, overexpression of MAEA in mouse hepatocytes has been shown to reduce hepatic gluconeogenesis, highlighting its potential as a therapeutic target for type 2 diabetes treatment." (PMID 40399988, 2025). "However, the associations of these loci except MAEA locus with type 2 diabetes have not been evaluated in independent East Asian cohorts." (PMID 24086726, 2013).
gastric cancer (4 papers, 2023 to 2025). A primary or metastatic malignant neoplasm involving the stomach. "To identify how MAEA KO altered gastric carcinoma growth versus survival, alone or together with alpelisib, we performed cell cycle analysis on propidium iodide stained cells." (PMID 38746323, 2024). "We validated by immunoblot that MAEA depletion increased MKLN1 and ZMNYD19 abundances in both YCCEL1 and SNU-719 EBV+ gastric carcinoma cells." (PMID 41315365, 2025). "MAEA KO reduced phosphorylation of mTOR targets S6K kinase and 4E-BP1 in both YCCEL1 and SNU-719 EBV+ gastric carcinoma cells and in HEK-293T." (PMID 41315365, 2025). "In summary, our study first discovered the malignant tumor-promoting role of LAD1 in gastric cancer and discovered a novel mechanism of LAD1 inhibiting the ubiquitination of Vimentin mediated by MAEA." (PMID 37718450, 2023). "Additionally, we discovered that LAD1 can promote chemoresistance in gastric cancer in vitro and in vivo, LAD1 targeting can promote chemosensitivity, and LAD1 can stabilize Vimentin by reducing MAEA-mediated ubiquitination." (PMID 37718450, 2023).
myeloproliferative disease (3 papers, 2021 to 2025). "Here the authors show that MAEA is required in HSCs for ubiquitination and downregulation of surface cytokine receptors via autophagy; MAEA loss leads to impaired HSC quiescence and a myeloproliferative disorder." (PMID 33947846, 2021).
glioblastoma (2 papers, 2025). The most malignant astrocytic tumor (WHO grade IV). "Another recent report demonstrated that MAEA can facilitate PHD3 ubiquitin-mediated degradation, ultimately favoring glioblastoma progression through enhanced stemness and the augmentation of temozolomide resistance." (PMID 39990651, 2025).
asthma (1 paper, 2023). "Among the differentially co-expressed genes, eight were previously linked to asthma in genome- (MRPL14, ASB3, RHOBTB2) and epigenome-wide (CLC, EPS15, GPI, SSCRB4, STRN4) association studies and five were mentioned in the literature in the context of asthma (SLC19A1, MAEA, CLC, ATP1B1, and RECK)." (PMID 36835202, 2023).
colorectal cancer (1 paper, 2025). A primary or metastatic malignant neoplasm that affects the colon or rectum. "Our analysis revealed that MAEA is significantly expressed in macrophages within the tumor microenvironment of colorectal cancer tissues." (PMID 39990651, 2025).
hepatocellular carcinoma (1 paper, 2022). A malignant tumor that arises from hepatocytes. "MAEA, one of the top 10 down-regulated proteins, has been reported to promote autophagy in brain cells, fibroblasts, hepatocellular carcinoma cells 42-44 and thus was identified as the potential target." (PMID 35342354, 2022).
lymph node metastasis (1 paper, 2025). "In CRC, low MAEA levels were also significantly associated with lymph node metastasis, distant metastasis, higher TNM stage, and higher CEA levels." (PMID 39990651, 2025).
osteosarcoma (1 paper, 2025). A usually aggressive malignant bone-forming mesenchymal neoplasm, predominantly affecting adolescents and young adults. "Given RUNX2’s involvement in transcriptional networks associated with metabolism and tumor progression, it may serve as an upstream regulator of MAEA or its related pathways, thereby modulating chemotherapy resistance in tumors such as osteosarcoma." (PMID 40989695, 2025).
cancer (7 papers, 2021 to 2025). A tumor composed of atypical neoplastic, often pleomorphic cells that invade other tissues. "COL27A1, PRUNE2, MAEA, TBC1D3, GADD45B, ANXA8 and TSPY1 have been confirmed to play a pro‐resistant role in various cancers, which reflects the reliability of the hGeCKO library screening to some extent." (PMID 39550701, 2024). "MAEA expression was quite consistently upregulated and showed up to 4-times higher expression in PDAC organoid lines compared to the single non-cancer control." (PMID 33820913, 2021). "Interestingly, only the cancer progenitor cells highly express cell-to-cell interaction-related genes, for example, ICAM4, MAEA, ITGA4, which are critical in establishing the stem cell niche for erythropoiesis." (PMID 38649187, 2024).
tumor (2 papers, 2025). "Gene Ontology (GO) analyses of the genes differentially expressed when comparing these two tumor types revealed that MAEA is most closely associated with DNA repair and the positive regulation of apoptotic signaling." (PMID 39990651, 2025). "Moreover, MAEA has been implicated in promoting autophagy, a process known to contribute to tumor cell survival and drug tolerance." (PMID 40989695, 2025). "While MAEA in macrophages might be involved in immune regulation and shaping the tumor microenvironment, its expression in tumor cells may be more directly linked to oncogenic pathways or tumor progression." (PMID 39990651, 2025). "When THP1 cells overexpressing MAEA were differentiated into macrophages, elevated levels of this E3 ligase were found to promote significantly enhanced macrophage-mediated tumor cell phagocytosis." (PMID 39990651, 2025). "IHC staining revealed that MAEA significantly reduced Ki67 expression and promoted cleaved caspase-3 expression in GC and CRC tumor cells." (PMID 39990651, 2025). "Consistently, IHC analyses of 169 GC tumor tissue samples revealed that the OS and DFS of patients with high MAEA levels were significantly better than those of patients with low levels of MAEA expression." (PMID 39990651, 2025). "Here, MAEA was found for the first time to promote PARP1 ubiquitination and degradation, in turn suppressing tumor cell proliferation and chemoresistance." (PMID 39990651, 2025). "Intriguingly, in gastrointestinal cancers, MAEA overexpression paradoxically enhances chemosensitivity via promoting PARP1 ubiquitination and degradation, suggesting that MAEA’s influence on chemotherapy response is tumor type- and context-specific." (PMID 40989695, 2025). "Such MAEA overexpression significantly suppressed the sphere-forming and colony-forming abilities of these tumor cells in the presence or absence of oxaliplatin." (PMID 39990651, 2025). "MAEA overexpression also led to a significant drop in the proliferation of tumor cells that were or were not treated with oxaliplatin, in addition to significantly reducing the oxaliplatin IC50 value for these cell lines." (PMID 39990651, 2025).
MAEA also shares sentences with these, for which no sentence is quoted: anemia (2 papers); diabetes (2); Insulin resistance (2); colon cancer (1); GI tumor (1); idiopathic pulmonary fibrosis (1); infection (1); Intellectual disability (1); osteoporosis (1); parasitic diseases (1); peanut allergy (1); pheochromocytoma (1).